CRTAM (cytotoxic and regulatory T cell molecule)
Description:
Mediates heterophilic cell-cell adhesion which regulates the activation, differentiation and tissue retention of various T-cell subsets (By similarity). Interaction with CADM1 promotes natural killer (NK) cell cytotoxicity and IFNG/interferon-gamma secretion by CD8+ T-cells in vitro as well as NK cell-mediated rejection of tumors expressing CADM1 in vivo. Regulates CD8+ T-cell proliferation in response to T-cell receptor (TCR) activation (By similarity). Appears to be dispensable for CD8+ T-cell-mediated cytotoxicity (By similarity). Interaction with SCRIB promotes the late phase of cellular polarization of a subset of CD4+ T-cells, which in turn regulates TCR-mediated proliferation and IFNG, IL17 and IL22 production (By similarity). By interacting with CADM1 on CD8+ dendritic cells, regulates the retention of activated CD8+ T-cells within the draining lymph node (By similarity). Required for the intestinal retention of intraepithelial CD4+ CD8+ T-cells and, to a lesser extent, intraepithelial and lamina propria CD8+ T-cells and CD4+ T-cells (By similarity). Interaction with CADM1 promotes the adhesion to gut-associated CD103+ dendritic cells, which may facilitate the expression of gut-homing and adhesion molecules on T-cells and the conversion of CD4+ T-cells into CD4+ CD8+ T-cells (By similarity).
Synonyms: CD355
Tractability: Antibody: its Gene Ontology location is reachable by antibodies, with high confidence; UniProt places it where antibodies can reach, with medium confidence; UniProt predicts a signal peptide or a membrane-spanning region.
Gene: Protein-coding gene on chromosome 11 (122,829,482 to 122,872,643, forward strand). Ensembl gene ENSG00000109943.
Subcellular location: Cell membrane
Pathways (Reactome):
Immune System: Immunoregulatory interactions between a Lymphoid and a non-Lymphoid cell
Gene Ontology:
Molecular function: protein binding; signaling receptor binding
Biological process: activated T cell proliferation; cell recognition; detection of stimulus; detection of tumor cell; positive regulation of cytokine production; positive regulation of natural killer cell mediated cytotoxicity; positive regulation of natural killer cell mediated cytotoxicity directed against tumor cell target; T cell mediated cytotoxicity; establishment of T cell polarity; heterophilic cell-cell adhesion; lymphocyte migration into lymphoid organs; negative regulation of activated T cell proliferation; positive regulation of type II interferon production; regulation of CD8-positive, alpha-beta T cell activation; regulation of T cell activation; regulation of T cell differentiation
Cellular component: plasma membrane; immunological synapse
Genetic constraint (gnomAD): Loss-of-function variants: 30 observed, 35.86 expected, observed/expected ratio (o/e) 0.84, 90% interval 0.62 to 1.13. The upper end of that interval is the gene's LOEUF score, 1.13, which puts it in group 4 of 6, group 1 being the genes least tolerant of losing a copy. Missense variants: 357 observed, 397.08 expected, observed/expected ratio (o/e) 0.9, 90% interval 0.82 to 0.98. Synonymous variants: 132 observed, 150.7 expected, observed/expected ratio (o/e) 0.88, 90% interval 0.76 to 1.01.
Homologues: Orthologues: chimpanzee CRTAM (99% identical), macaque CRTAM (92% identical), dog CRTAM (79% identical), rabbit CRTAM (76% identical), pig CRTAM (75% identical), mouse Crtam (72% identical), guinea pig CRTAM (70% identical), rat Crtam (70% identical), tropical clawed frog crtam (38% identical), Drosophila melanogaster Fas3 (13% identical). Paralogues in human: CADM2 (17% identical), CADM3 (17% identical), CADM1 (16% identical), CADM4 (15% identical), NECTIN1 (15% identical), NECTIN4 (15% identical), NECTIN2 (14% identical), PVR (14% identical), NECTIN3 (12% identical), CD200 (11% identical), CD226 (11% identical), TIGIT (8% identical), and 2 more.